HMGCS2 (3-hydroxy-3-methylglutaryl-CoA synthase 2)
Description:
Catalyzes the first irreversible step in ketogenesis, condensing acetyl-CoA to acetoacetyl-CoA to form HMG-CoA, which is converted by HMG-CoA reductase (HMGCR) into mevalonate.
Tractability: Small molecule: a structure with a bound ligand is known; it has a high-quality binding pocket. PROTAC: ubiquitination databases record sites on it.
Safety:
Unwanted effects reported when the protein is acted on. In parentheses: how it was acted on, where the effect was seen, and who reports it.
Increased, Liver Steatosis (inhibition; source: AOP-Wiki)
increase in blood glucose (source: ClinPGx)
Gene: Protein-coding gene on chromosome 1 (119,747,979 to 119,769,092, reverse strand). Ensembl gene ENSG00000134240.
Subcellular location: Mitochondrion
Subcellular location (Human Protein Atlas): Mitochondria
Pathways (Reactome):
Metabolism: PPARA activates gene expression; Synthesis of Ketone Bodies
Metabolism of proteins: Mitochondrial protein degradation
Gene Ontology:
Molecular function: hydroxymethylglutaryl-CoA synthase activity; identical protein binding; acyltransferase activity
Biological process: acetyl-CoA metabolic process; ketone body biosynthetic process; farnesyl diphosphate biosynthetic process, mevalonate pathway; adipose tissue development; cellular response to amino acid stimulus; cellular response to fatty acid; cellular response to glucocorticoid stimulus; cellular response to hormone stimulus; cellular response to insulin stimulus; cellular response to lipopolysaccharide; isoprenoid biosynthetic process; kidney development; liver development; lung development; midgut development; multicellular organismal response to stress; response to bacterium; response to cAMP; response to ethanol; response to fatty acid; response to glucagon; response to glucocorticoid; response to growth hormone; response to insulin; response to linoleic acid; and 10 more
Cellular component: mitochondrion; mitochondrial matrix
Genetic constraint (gnomAD): Loss-of-function variants: 48 observed, 54.94 expected, observed/expected ratio (o/e) 0.87, 90% interval 0.69 to 1.11. The upper end of that interval is the gene's LOEUF score, 1.11, which puts it in group 4 of 6, group 1 being the genes least tolerant of losing a copy. Missense variants: 622 observed, 659.72 expected, observed/expected ratio (o/e) 0.94, 90% interval 0.88 to 1.01. Synonymous variants: 251 observed, 254.19 expected, observed/expected ratio (o/e) 0.99, 90% interval 0.89 to 1.1.
Gene-disease validity (ClinGen):
ClinGen rates the evidence that HMGCS2 causes each of these diseases.
3-hydroxy-3-methylglutaryl-CoA synthase deficiency (autosomal recessive): Definitive.
Homologues: Orthologues: chimpanzee HMGCS2 (99% identical), macaque HMGCS2 (97% identical), mouse Hmgcs2 (89% identical), dog HMGCS2 (89% identical), rat Hmgcs2 (89% identical), guinea pig HMGCS2 (88% identical), rabbit HMGCS2 (85% identical), pig HMGCS2 (85% identical), Drosophila melanogaster Hmgs (54% identical), Caenorhabditis elegans hmgs-1 (39% identical). Paralogues in human: HMGCS1 (62% identical).
Diseases named in the same sentence as HMGCS2 in open-access papers:
HMGCS2 is named in the same sentence as 110 diseases in open-access papers, as found by Europe PMC text mining. Sharing a sentence is not in itself a finding about the gene and the disease. The quoted sentences say what the papers report.
prostate carcinoma (18 papers, 2017 to 2025). A carcinoma that arises from epithelial cells of the prostate gland. "In prostate cancer, HMGCS2 and sterol synthesis have been implicated in tumor growth and progression by co‐culture with cancer‐associated fibroblasts." (PMID 38923428, 2024). "HMGCS2 protein expression was also reduced in prostate cancer tissues and low mRNA expression was associated with high pathological grade as well as the presence of distant metastases." (PMID 36432618, 2022). "HMGCS2 protein expression was significantly reduced in prostate cancer tissues, and low HMGCS2 expression was associated with a high Gleason score, pathological grade, and presence of distant metastasis in prostate cancer." (PMID 31886185, 2019). "Additionally, in vitro, co-culture of prostate cancer cells with cancer-associated fibroblasts upregulates expression of multiple genes of the cholesterol biosynthesis pathway, with HMGCS2 being the most upregulated." (PMID 34298684, 2021). "In contrast, a tumor-suppressive role as well as a tumor-promoting role have been demonstrated for HMGCS2 in breast cancer and prostate cancer in different studies." (PMID 40305364, 2025). "Low HMGCS2 expression is a poor prognostic factor in colorectal cancer, esophageal squamous cell carcinoma, prostate cancer, and hepatocellular carcinoma." (PMID 38923428, 2024). "HMGCS2 functions as a ketogenic rate-limiting enzyme and plays oncogenic roles in hepatocellular carcinoma and prostate cancer." (PMID 35875087, 2022). "HMGCS2 is differentially expressed between hormone-sensitive and hormone-resistant prostate cancer samples and belongs to a regulatory network in CRPC." (PMID 36611998, 2022). "Conversely HMGCS2, identified as tumor suppressor with prognostic impact in prostate cancer, resulted downregulated also in intestinal gastric cancer subset." (PMID 34012923, 2021). "With respect to tumor cell proliferation and tumor growth, in vitro studies have shown that HMGCS2 downregulation inhibits prostate cancer cell proliferation in 2D cultures and of 3D spheroid growth." (PMID 34298684, 2021). "HMGCS2 is a tumor suppressor in prostate cancer, the knockdown of which promotes cell proliferation, colony formation, migration, and invasion of prostate cancer cells." (PMID 32117717, 2020). "This could also explain the observed ability of HMGCS2 to induce resistance to tamoxifen in breast cancer and to promote the growth of castration-resistant prostate cancer." (PMID 40305364, 2025). "A similar situation exists with regard to the role of HMGCS2 in prostate cancer." (PMID 40305364, 2025). "The role of HMGCS2 in breast cancer and prostate cancer is complicated because of the dependence of these cancers on steroid hormones whose synthesis might be promoted by HMGCS2-mediated cholesterol synthesis." (PMID 40305364, 2025). "In prostate cancer, HMGCS2 facilitates tumor progression by promoting cholesterol biosynthesis." (PMID 38965575, 2024). "HMGCS2 knockdown promoted cell proliferation, invasion, and migration of prostate cancer cells." (PMID 36432618, 2022). "Several proteins related to the ketogenesis pathway were overexpressed in prostate cancer cells, among which HMGCS2 was included; on this basis, some researchers demonstrated the direct interaction between PPARα and HMGCS2, resulting in Src activation and the promotion of malignancy and invasion." (PMID 29966227, 2018). "Higher HMGCS2 expression was found in estrogen receptor-negative breast cancer and aggressive prostate cancer." (PMID 36432116, 2022). "For example, HMGCS2 overexpression is a negative prognostic factor in breast cancer, rectal cancer, and prostate cancer." (PMID 31779269, 2019).
hepatocellular carcinoma (15 papers, 2019 to 2025). A malignant tumor that arises from hepatocytes. "MYC represses 3-hydroxymethylglutaryl-CoA synthase (HMGCS2) in colon cancer and decreased expression of HMGCS2 is found in ccRCC and hepatocellular carcinoma, associated with worse patient outcome." (PMID 35831624, 2022). "Recent studies have shown that knocking down HMGCS2 in hepatocellular carcinoma cells inhibits cell proliferation." (PMID 39859448, 2025). "Previous studies have shown that HMGCS2 promotes fatty acid α-oxidation and ketone production in hepatoma cells, playing a vital role in fatty acid oxidation and overall lipid metabolism." (PMID 40870032, 2025). "Previous studies found that HMGCS2 induced fatty acid α-oxidation and ketone production in hepatoma cells and played a crucial role in fatty acid oxidation." (PMID 36613828, 2022). "A previous study demonstrated that HMGCS2 expression was required for fatty acid oxidation in a hepatoma cell line." (PMID 32635582, 2020). "Administration of human hepatoma cells with hypercholestaerolaemic blood sera previously induced an increase in the mRNA expression of HMGCS2, an enzyme involved in the ketone body pathway." (PMID 32298312, 2020). "The collective data obtained from the clinical human specimens indicated that HMGCS2 protein expression is negatively correlated with disease progression and severity of hepatocellular carcinoma." (PMID 31779269, 2019). "In addition, studies have confirmed that SLC38A4 is a prospective biomarker with therapeutic goal that exerts tumor suppressive effects in hepatocellular carcinoma by modulating the Wnt/β-catenin/MYC/HMGCS2 axis." (PMID 37168445, 2023). "In a previous investigation, we demonstrated that cultured hepatoma cells treated with hypercholesterolaemic sera compared with cells treated with normocholesterolaemic sera show overexpression of mRNAs related to mitochondrial 3-hydroxy-3-methylglutaryl-coenzyme A synthase (HMGCS2)." (PMID 32298312, 2020). "Although the detailed mechanism by which the ketogenic diet inhibited HCC tumor growth requires further investigation, our data provide new insight into HMGCS2-mediated ketone production as a nutritional therapy in the treatment of hepatocellular carcinoma." (PMID 31779269, 2019). "Although HMGCS2 expression was decreased in hepatoma cell lines and hepatocellular carcinoma patients, the regulation of ketogenesis by HMGCS2 remains unclear in HCC." (PMID 31779269, 2019).
diabetes (14 papers, 2017 to 2025). "Furthermore, Hmgcs2, Ucp3, and Pck1 are increased and expressed in Akita mice hearts, and these highly interacting DEGs correlate with their cardiac expression and the importance of their functions in numerous signalling pathways associated with cardiomyopathy in diabetes." (PMID 41007634, 2025). "HMGCS2 has been suggested to play important roles in diabetes, tumor, Alzheimer's disease, and intestinal cell differentiation." (PMID 36629048, 2023). "Increased HMGCS2 expression in diabetes enhanced the production of ketone bodies, thus leading to diabetic cardiomyopathy, whereas the function of HMGCS2 in diabetic nephropathy remains controversial." (PMID 36629048, 2023). "Among the top upregulated genes in response to HFD/STZ-induced diabetes within each cell population were transcripts for Pdk4, Angptl4, Txnip, Postn, Hmgcs2, and Ucp3, of which several have been previously involved in heart failure." (PMID 37010266, 2023). "HMGCS2 is a mitochondrial enzyme that catalyzes the first reaction of ketogenesis and related research has mainly focused on its roles in diabetes, tumor, Alzheimer's disease, and intestinal cell differentiation." (PMID 36629048, 2023). "Inhibition of HMGCS2 expression was reported to reduce endothelial damage in a diabetes mellitus model." (PMID 32298312, 2020). "Interestingly, we found sex-divergent differences in Hmgcs2 expression following maternal diabetes + HFD exposure." (PMID 36835096, 2023). "Given that hyperuricemia is the second most prevalent metabolic disorder after diabetes, the increased expression of HMGCS2 in hyperuricemic mice may indicate its potential role in hyperuricemia-induced oxidative stress and mitochondrial dysfunction, ultimately leading to cardiac dysfunction." (PMID 40361044, 2025). "The findings imply that enhanced renal ketogenesis due to Hmgcs2 overexpression may be significant in the pathogenesis of diabetic neuropathy DN in patients with type 2 diabetes, indicating that Hmgcs2 is a potential therapeutic target for the management of diabetic renal complications." (PMID 36851058, 2023). "Therefore, our next experiments were designed to determine whether HMGCS2 expression was increased by diabetes only in the heart or other vital organs such as the liver, kidney and spleen." (PMID 28676675, 2017). "After menopause, the protection seems to weaken in females and the onset of diabetes induces changes in renal gene expression patterns, including those related to mitochondrial metabolism or FAO (Crot, Aldh1a1, Hmgcs2, Acadm)." (PMID 35230975, 2022). "Nonetheless, in hypertrophic left ventricle (LV) myocardium from individuals without coexisting diabetes, we found upregulation of HMGCS2 staining compared with age and sex-matched healthy donor hearts." (PMID 40211954, 2025). "Western blot validation of several proteins with high pathophysiological importance, including MYH7, HMGCS2, PDK4, and BDH1, indicated that mass spectrometry was able to qualitatively, but not quantitatively, reflect the fold changes of certain proteins in diabetes." (PMID 39539089, 2024). "To determine the effects of maternal diabetes + HFD on levels of enzymes needed for ketone body metabolism, we examined the gene expression of 3-hydroxy-3-methylglutaryl-CoA synthase 2 (Hmgcs2) and β-hydroxy butyrate dehydrogenase (Bdh1) in neonatal myocardium." (PMID 36835096, 2023). "Overall, sex-related differences in Hmgcs2 and Bdh1 expression are found only in diabetes + HFD-exposed myocardium, but not in controls." (PMID 36835096, 2023).
breast carcinoma (11 papers, 2010 to 2025). "Recently, Wang and co-authors using Illumina expression array/RT PCR analysis sought to identify risk biomarkers that are specific to ER status of breast cancer and among several others revealed a significant overexpression of HMGCS2 in ER- cases." (PMID 25389781, 2014). "Breast cancer cells themselves also express HMGCS2, where the enzyme is associated with resistance to endocrine therapy with tamoxifen, but the mechanism underlying the link between HMGCS2 and tamoxifen resistance seems to be related to changes in mitochondrial oxidative stress." (PMID 40305364, 2025). "Interestingly, mitochondrial HMGCS2, which encodes for an enzyme of the ketogenic pathway, increases 27-fold from T1 to T7 and its expression controls differentiation in colon and breast cancer cells." (PMID 29662633, 2018). "Overexpression of HMGCS2 also increased the metastatic ability of breast cancer cells, MDA-MB-231, as reported by Martinez-Outschoorn and colleagues." (PMID 39859448, 2025). "In breast cancer, meanwhile, HMGCS2 promotes cell growth by augmenting mitochondrial oxidative stress and has emerged as a potential pharmacological target in this malignancy." (PMID 38965575, 2024). "In view of this fact, we examined the expression of FABP7 and HMGCS2 together with several other apocrine protein markers in the MDA-MB-453 breast cancer cell line." (PMID 25389781, 2014). "Several of these genes have been linked to breast cancer (MAPT, HMGCS2, NR2F2, TFAP2B, NTN4, SEC14L2 and LTF)." (PMID 21209903, 2010). "In breast cancer cells, overexpression of HMGCS2 is considered an adverse prognostic factor." (PMID 39859448, 2025). "Moreover, ketogenic fibroblasts overexpressing HMGCS2 enhance the growth of co-injected MDA-MB-231 breast cancer cells in vivo." (PMID 34829786, 2021). "RT-qPCR of select cancer-related genes in both shRING1B T47D and MDA-MB-231 cells confirmed the RNA-seq results, and further suggested that fatty acid metabolism (represented by CD36 and HMGCS2) may play a major role in the tumorigenesis of ER+ breast cancer." (PMID 30139998, 2018). "Moreover, our results demonstrate that HMGCS2 added to the steroid hormone receptor signature (ER-/PR-/AR+) identifies apocrine tumors from other breast cancer subtypes with greater sensitivity as compared to steroid receptor profile alone." (PMID 25389781, 2014). "HMGCS2 was expressed in 1 out of 42 TNBCs (2,38%); 18 out of 101 Luminal A (17,8%); 4 out of 17 Luminal B (23,5%) and 11 out of 43 HER2+ (25,5%), in total: 34 out of the 203 non-apocrine breast carcinomas (16,7%)." (PMID 25389781, 2014).
colon cancer (11 papers, 2009 to 2025). "We found that elevated OXCT1 in aggressive BCa parallels levels in patients with colon cancer and HMGCS2 loss promoting tumor progression." (PMID 39509334, 2024). "In poorly differentiated colon cancer, HMGCS2 protein expression was downregulated, while higher HMGCS2 expression caused poor susceptibility of rectal cancer to chemoradiotherapy." (PMID 36432116, 2022). "Some studies have shown that HMGCS2 promotes migration, invasion, and metastasis of colon cancer cells and that the underlying mechanism is ketogenesis-independent and involves direct interaction of HMGCS2 protein with the nuclear receptor PPARα and resultant expression of the oncogene Src." (PMID 40305364, 2025). "However, in the context of chemotherapy (i.e., oxaliplatin), elevated HMGCS2 expression in the epithelia is associated with colon cancer recurrence." (PMID 39509334, 2024). "It has been documented that in colon cancer tissue specimens, the expression level of HMGCS2 negatively correlates with microvessel density, indicating the impact of tumor-cell HMGCS2 on tumor angiogenesis." (PMID 40305364, 2025). "The impact of HMGCS2 expression level in colon cancer cells is not limited to its local effects within the cancer cell; it also influences the tumor microenvironment." (PMID 40305364, 2025). "In colon cancer cells, HMGCS2 suppresses differentiation and proliferation and also reprograms metabolic pathways." (PMID 40305364, 2025). "Using a genome-scale metabolic model, we demonstrated that HMGCS2 suppression increased glycolysis, lipid biosynthesis, and elongation while decreasing fatty acid oxidation in colon cancer cells." (PMID 37692839, 2023). "Inhibition of the Wnt/β-catenin pathway resulted in increased protein and mRNA expression of HMGCS2 and βHB production in human colon cancer cell lines LS174T and Caco2." (PMID 31546785, 2019). "On the other hand, HMGCS2 downregulation indicates poor outcomes in esophageal squamous cell carcinoma and colon cancer." (PMID 31779269, 2019). "In particular, it has been reported that HMGCS2 expression was repressed by c-Myc, which is activated by the Wnt/β-catenin pathway, in colon cancer cells." (PMID 31546785, 2019). "Decreased expression of HMGCS2 in colon cancer cells leads to suppression of fatty acid oxidation, increased dependence on glucose for energy, potentiation of fatty acid synthesis, and other metabolic phenotypes that are characteristic of highly proliferating cancer cells." (PMID 40305364, 2025). "In colon cancer, most studies have shown a tumor-suppressive function for HMGCS2." (PMID 40305364, 2025). "In poorly differentiated colon cancer, HMGCS2 protein expression was downregulated." (PMID 31779269, 2019). "In colon cancer cell lines, β-oxidation and HMGCS2 expression are impaired." (PMID 19707587, 2009). "However, the role of HMGCS2 in colon cancer is not without controversy." (PMID 40305364, 2025).